IL6 (interleukin 6)
Diseases named in the same sentence as IL6 in open-access papers (continued):
Sharing a sentence is not in itself a finding about the gene and the disease.
acute laryngitis (2 papers, 2021 to 2024). An acute inflammatory process affecting the larynx. "Multivariate logistic regression analysis showed that the tumor necrosis factor-alpha, interleukin (IL)-4, IL-6, IL-17, and interferon-gamma levels were risk factors for acute laryngitis complicated by laryngeal obstruction." (PMID 39969319, 2024). "Multivariate logistic regression analysis indicated that TNF-α, IL-4, IL-6, IL-17, and IFN-γ were risk factors for the efficacy of treatment in children with acute laryngitis and laryngeal obstruction after adjustment for confounders, such as age and gender." (PMID 39969319, 2024).
acute rheumatic fever (2 papers, 2021). "Inflammatory cytokines, such as TNFɑ, IL-8, and IL-6, may play a pathogenic role in rheumatic fever." (PMID 33638745, 2021). "However, interleukin-6 was shown to be involved in the pathogenesis of rheumatic fever." (PMID 33638745, 2021). "However, the efficacy of long-acting penicillin for secondary prevention of rheumatic fever has not been widely studied; consequently, the relation between serum levels of long-acting penicillin and inflammatory markers C-reactive protein and interleukin-6 is largely unknown." (PMID 33638745, 2021).
acute tonsillitis (2 papers, 2020). An acute inflammation of the tonsils caused by viruses or bacteria. "T-cells in palatine tonsils from adult patients with recurrent acute tonsillitis and peritonsillar abscess are functional and responsive and feature a characteristic, specific cytokine response with low IL-6 and features of Th1." (PMID 32747802, 2020). "Specifically, levels of TNF-α, IL-1, IL-6 are higher in the saliva of children with chronic tonsillitis, although statistically significant differences were only noted for the pro-inflammatory cytokine IL-618." (PMID 32747802, 2020). "Pediatric SDB is related to chronic inflammatory condition such as chronic tonsillitis and chronic adenoiditis, with raised in various inflammatory mediators, such as TNF-α, IL-1 and IL-6." (PMID 32393268, 2020).
acute transverse myelitis (2 papers, 2012 to 2024). Acute transverse myelitis (ATM) is an inflammatory demyelinating disorder of the spinal cord that can be either idiopathic (IATM) or secondary to a known cause (SATM). "Other researchers described a case of acute transverse myelitis that occurred after a COVID-19 infection similar to the one being discussed herein, and proposed to treat such patients using steroids and plasmapheresis or immunoglobulins in cases involving elevated IL-6 levels." (PMID 38921263, 2024).
Addison disease (2 papers, 2020 to 2025). "Increased levels of interleukin-6 were reported not only in patients with Addison disease, but also in patients with both primary and secondary AI, suggesting that increased concentration of interleukin-6 are a consequence of not only autoimmune destruction of the adrenal cortex." (PMID 39240753, 2025).
adenopathies (2 papers, 2021 to 2025). "The first presented patient obtained a prompt resolution of symptoms and a complete regression of adenopathies after IL-6 blockade therapy administration." (PMID 33676575, 2021). "Computed tomography (CT) scan performed after 6 months of anti-IL-6 therapy indicated a complete regression of all previously reported adenopathies." (PMID 33676575, 2021). "The clinical presentation was mostly driven by the appearance of an isolated enlarged adenopathy, without associated inflammatory syndrome, although IL‐6 plasma levels were frequently elevated." (PMID 41210897, 2025).
Age-related cataract (2 papers, 2016 to 2023). A type of cataract (opacification of the lens) that forms during the course of aging. "In addition, one population-based study showed that several systemic inflammatory mediators (high sensitivity C-reactive protein, tumor necrosis factor α, interleukin-6, and intracellular adhesion molecule-1), were associated with age-related cataracts." (PMID 27861567, 2016).
Ageusia (2 papers, 2022 to 2023). A rare condition that is characterized by a complete loss of taste function of the tongue. "The Wilcoxon rank test displayed a statistically significant difference in IL-6 levels in moderate vs mild patients with ageusia, hypogeusia (score), and parageusia (p < 0.05)." (PMID 35801415, 2023).
amnesia (2 papers, 2018 to 2021). Pathologic partial or complete loss of the ability to recall past experiences ( AMNESIA, RETROGRADE) or to form new memories ( AMNESIA, ANTEROGRADE). "Genetic ablation of IL-6 in mice yields improved memory formation as IL-6 knockout mice were less sensitive to scopolamine-induced amnesia." (PMID 30374291, 2018).
angle-closure glaucoma (2 papers, 2017 to 2024). The sudden increase of intraocular pressure, resulting in pain and an abrupt decrease in visual acuity. "Specifically, IL-6 was found to be upregulated in the tears of POAG patients and in the aqueous humor of angle-closure glaucoma (ACG) patients, respectively." (PMID 39458974, 2024). "There is some indication that modulation of IL-6 signaling accompanies IOP elevations in human patients, including both primary open angle and angle closure glaucoma." (PMID 28620279, 2017).
Apathy (2 papers, 2022). Apathy is a quantitative reduction of interest, motivation and the initiation and persistence of goal-directed behavior, where often the accompanying emotions, thoughts, and social interactions are also diminished. "Our bivariate analyses of the baseline characteristics revealed that dysphoria, IL-6, multimorbidity, and gait velocity were all significantly associated with higher levels of apathy, which we investigated further in regression models." (PMID 35742625, 2022). "Mediation analyses demonstrated that IL-6 modestly mediates the relationship between apathy and gait velocity, while apathy mediated the relationships between dysphoria and multimorbidity and gait velocity." (PMID 35742625, 2022). "The inflammatory biomarker IL-6 was significantly associated with the higher levels of apathy while CRP was not." (PMID 35742625, 2022). "In regression models, IL-6 but not CRP was associated with apathy." (PMID 35742625, 2022). "Among AD patients, compared with those without apathy, those with apathy had higher levels of interleukin-6, interleukin-10, and leptin." (PMID 36572691, 2022). "In our CCMA cohort, we found that IL-6 level, but not CRP, was significantly associated with apathy, which differs from Eurelings’ previous findings that CRP was associated with apathy in the PreDIVA trial." (PMID 35742625, 2022). "Linear and logic regression models showed that IL-6, but not CRP was significantly associated with apathy adjusted for age, gender, and years of education (β = 0.037, 95% CI: 0.002–0.072, p = 0.04)." (PMID 35742625, 2022).
arterial disease (2 papers, 2019 to 2022). "Concomitant arterial disease in mixed venous-arterial ulcers did not influence the levels of EGF, FGF-2, IL-1α, IL-1β, IL-6, PDGF, TGF-β1 and TNF-α in one study." (PMID 35742965, 2022).
arteriovenous malformations of the brain (2 papers, 2018 to 2023). "IL6 rs1800795 was proven to be a risk factor for various diseases, including arteriovenous malformations of the brain." (PMID 38275640, 2023).
asthenospermia (2 papers, 2022 to 2024). "In CTX induced asthenospermia mouse model, the levels of TNF-α and IL-6 in serum were higher than those in the control group (p < 0.01)." (PMID 36142279, 2022). "The asthenospermia mouse model showed high activity of MDA and proinflammatory factors (TNF-α, IL-6), as well as low expression of antioxidants (SOD, GSH-Px, CAT) in the testis and epididymis, but this situation could be significantly ameliorated after being treated with CNP." (PMID 36142279, 2022).
autoimmune disease of the nervous system (2 papers, 2021 to 2023). "Considering the critical role of IL-6-mediated inflammation in autoimmune neurological diseases, increased IL-6 levels in the GADA high-positive group may indicate a role for IL-6 in initiating, and propagating autoimmune inflammation in our patients." (PMID 37025699, 2023).
autoimmune retinopathy (2 papers, 2018 to 2023). An autoimmune disease characterized by sudden onset of photopsias and scotomata in patients with no family history of retinitis pigmentosa, followed by visual field and central vision loss. "Although their utility has been most documented in the treatment of NIU and NIU-related macular edema, the use of IL-6 inhibitors might be extended to inflammatory CME in the context of complications from cataract surgery, acute retinal necrosis, and autoimmune retinopathy." (PMID 36902105, 2023).
autoimmune type 1 diabetes (2 papers, 1995 to 2022). Autoimmune disease wherein the body's own immune system attacks and destroys the cells within the pancreas that produce insulin. "Therefore, injury of pancreatic β-cells and possible induction of autoimmune type 1 diabetes via various cytokines may be caused by IL-6 or IFN-γ, or by their ability to induce MHC class II antigen upregulation." (PMID 18475668, 1995). "Increased STAT3 (Tyr705) phosphorylation after IL-6 stimulation was recently described in patients with autoimmune type 1 diabetes, and this increased responsiveness was seen both for CD4+ and CD8+ T cells." (PMID 35566660, 2022).
autoimmune vasculitis (2 papers, 2021 to 2025). An autoimmune form of vasculitis. "Conversely, emerging topics such as cardiac amyloidosis, interleukin-6 (IL-6)-mediated myocardial injury, and autoimmune vasculitis are situated within the “niche themes” quadrant, reflecting their increasing relevance and capacity to shape future research directions." (PMID 40661822, 2025).
Azoospermia (2 papers, 2024 to 2025). Absence of any measurable level of sperm,whereby spermatozoa cannot be observed even after centrifugation of the semen pellet. "Immunofluorescence staining of the testes revealed that the histone methyltransferase EZH2 and Leydig cell marker gene IL6 or HDAC2 were upregulated in azoospermia." (PMID 40756901, 2025).
B-cell neoplasm (2 papers, 2009 to 2022). A group of heterogeneous lymphoid tumors generally expressing one or more B-cell antigens or representing malignant transformations of B-lymphocytes. "Overactive IL6 is a characteristic of B cell neoplasms and conditions such as Multicentric Castleman’s disease." (PMID 35213597, 2022).
benign breast tumor (2 papers, 2022 to 2023). "This study's results showed that the serum IL-6 level was significantly higher in patients with GLM than in those with benign breast tumors." (PMID 37817809, 2023). "IL-6, NEU, NEU%, and CRP values were significantly elevated in patients with GLM compared to those with benign breast tumors, indicating that IL-6 plays an important role in the development and onset of GLM." (PMID 37817809, 2023). "Serum IL-6 levels were significantly higher in patients with GLM than in those with benign breast tumors (P < 0.01)." (PMID 37817809, 2023). "The correlation between these cytokines and the development and progression of benign breast tumors needs to be further explored, as cytokines such as IL-6 may provide effective markers for the treatment of GLM." (PMID 37817809, 2023). "Correlation analysis between IL-6 and inflammatory indicators in patients with benign breast tumor." (PMID 37817809, 2023). "Based on this finding, this study aimed to further explore the differences and significance of IL-6 in the development of GLM and benign breast tumors to provide new ideas and bases for clinical diagnosis and treatment." (PMID 37817809, 2023). "The correlation between IL-6 and TNF-α was more significant in patients with benign breast tumors than in those with GLM patients, which is worth noting and requires further research." (PMID 37817809, 2023). "The average serum IL-6 concentration in patients with GLM was 2.99 ± 3.34 pg/ml, which was significantly higher than that in patients with benign breast tumors (P < 0.01)." (PMID 37817809, 2023). "This study aimed to explore the differences and significance of peripheral blood IL-6 and related cytokines, routine blood test results, and C-reactive protein (CRP) levels between patients with GLM and benign breast tumors." (PMID 37817809, 2023). "In the present study, we further investigated the differences in the peripheral blood inflammatory indicator IL-6 and other cytokines in patients with GLM and those with benign breast tumors, which provided an innovative idea for exploring the pathogenesis, clinical diagnosis, and treatment of GLM." (PMID 37817809, 2023). "It is unclear whether the mechanism of the interleukin (IL)-6 signaling pathway is similar between granulomatous lobular mastitis (GLM) and benign breast tumors." (PMID 37817809, 2023). "Existing studies have confirmed that the IL-6/JAK/STAT3 signaling pathway is crucial for the proliferation and survival of tumor cells; however, it is unclear whether this pathway plays a similar role in GLM formation and whether its mechanism is similar to that in benign breast tumor." (PMID 37817809, 2023).
beta thalassemia (2 papers, 2019 to 2022). Beta-thalassemia (BT) is characterized by deficiency (Beta+) or absence (Beta0) of synthesis of the beta globin chains of hemoglobin (Hb). "Our results of reduced IL-6, IL-10, and IL-8 serum levels in beta thalassemia disagree with findings of previous studies in this field, which are themselves controversial, probably due to differences in patient populations and therapies." (PMID 36699704, 2022).
bilateral progressive sensorineural hearing loss (2 papers, 2022 to 2025). "We identified a ZNF334 truncation mutation (p.Thr399fs) in a rare case of late-onset cold-induced autoinflammatory disease with elevated TNF-α, IL-1β, IL-6, and extracellular heat shock protein 90 (eHsp90) plasma levels and progressive sensorineural hearing loss." (PMID 41168503, 2025).
bile reflux (2 papers, 2015 to 2022). "Bile reflux can promote gastric carcinogenesis through the activation of the IL‐6/JAK1/STAT3 pathway and STAT3 inhibition can alleviate this carcinogenic effect." (PMID 35285172, 2022).
biliary atresia (2 papers, 2019 to 2021). A rare, biliary tract disease characterized by progressive obliterative cholangiopathy of the intra- and extrahepatic bile ducts, occurring in the embryonic/ perinatal period, leading to severe and persistent neonatal jaundice and acholic stool. "It is consistent with higher IL-2, IL-4, IL-6, IL-10, TNFα, and IFN-γ in patients with biliary atresia." (PMID 34630385, 2021).
bone metabolism disorders (2 papers, 2021 to 2024). "For example, an earlier study applied an interactome analysis approach and identified leptin, tumour necrosis factor, interleukin-6 (IL-6) and parathyroid hormone as candidate biomarkers for CVDs and bone metabolism disorders in CKD patients." (PMID 33725119, 2021). "Proinflammatory cytokines, including TNFα, IL6, IL18, IL17, and CRP appear to activate osteoclasts and osteoblasts, leading to bone metabolism disorders." (PMID 38272859, 2024).
burn (2 papers, 2021 to 2024). A traumatic injury involving interruption of tissue cohesiveness that results from exposure to caustic chemicals, extreme heat, extreme cold or excessive radiation. "Burn injuries resulted in a markedly higher level of IL-1β and IL-6 production in the serum (P < 0.01)." (PMID 33985568, 2021). "Burn patients showed a decreased enrichment of H3K9me2 in CXCL8, IL-17, and TNFA promoters, whereas IL-6, FOS, and IL-1B promoters displayed an H3S28p enrichment diminution during the first 10 days post-burn." (PMID 39768289, 2024).
cardiac amyloidosis (2 papers, 2025). Cardiac amyloidosis is a condition whereby cardiac tissue is infiltrated by amyloid fibrils. "The growing prominence of cardiac amyloidosis, IL-6-mediated inflammation, and advanced imaging reflects a shifting paradigm toward precision diagnostics and immunomodulatory therapies." (PMID 40661822, 2025). "PON3, SIGLEC1, and IL-6 demonstrated a statistically non-significant trend of a weak-to-moderate association with MACE in cardiac amyloidosis." (PMID 41007815, 2025).
carditis (2 papers, 2011 to 2025). "The plasma levels of IL-6 were higher in ARF patients with carditis than in healthy controls." (PMID 41305420, 2025). "From a translational perspective, IL-6 and IL-8 may serve as potential diagnostic biomarkers, while targeting IL-1β or CXCR3-dependent signaling could represent therapeutic avenues to mitigate inflammation associated with carditis." (PMID 41305420, 2025).
carpal tunnel syndrome (2 papers, 2012 to 2020). Entrapment of the median nerve in the wrist that is characterized by numbness, tingling and painful movement. "Other labs have also observed increased inflammatory cytokines in tendons with overuse, in association with carpal tunnel syndrome, or after prolonged exercise, including increased IL-1beta and IL-6." (PMID 23056540, 2012). "In fact, some studies have demonstrated that patients with neuropathic pain due to intervertebral disc herniation or the carpal tunnel syndrome had increased serum IL-6 and TNF." (PMID 32038662, 2020).
cerebral amyloid angiopathy (2 papers, 2021 to 2022). "It has been shown that biomarkers of systemic inflammation, like IL-6, may be associated with a specific form of SVD, the cerebral amyloid angiopathy (CAA) also known as type 2 SVD, which involves lobar regions and the centrum semiovale." (PMID 35486344, 2022).
Chorea (2 papers, 2020). Chorea (Greek for 'dance') refers to widespread arrhythmic involuntary movements of a forcible, jerky and restless fashion. "Studies have shown that HD skeletal muscle is hyperexcitable, which can cause involuntary and prolonged contractions that may contribute to chorea and could produce elevated levels of IL-6." (PMID 32887270, 2020).
chronic headache (2 papers, 2014 to 2022). "Pentraxin-3 and interleukin-6 (IL-6) have already been recognized as biomarkers for headache syndromes." (PMID 35498555, 2022). "Acupuncture significantly reduces plasma levels of TNF-α in patients with chronic headache and mRNA levels of IL-6 and IL-1β in rats of lipopolysaccharide-induced fever." (PMID 24991226, 2014).
chronic meningitis (2 papers, 2013 to 2015). Chronic form of meningitis (disease). "We suggest that all patients with non-infective chronic meningitis of unknown etiology should be investigated for IL-6 hypersecretion." (PMID 23432807, 2013).
chronic myelomonocytic leukemia (2 papers, 2021 to 2024). A myelodysplastic/myeloproliferative neoplasm which is characterized by persistent monocytosis, absence of a Philadelphia chromosome and BCR/ABL fusion gene, fewer than 20 percent blasts in the bone marrow and blood, myelodysplasia, and absence of PDGFRA or PDGFRB rearrangement. "Bryostatin-1 induced proinflammatory cytokines such as IL-8, IL-1β, TNF-α, and IL-6 in human monocytes and increased TNF-α secretion of chronic myelomonocytic leukemia cells." (PMID 39877358, 2024).
chronic recurrent multifocal osteomyelitis (2 papers, 2017 to 2025). "Serum CCL11/eotaxin and IL-6 allow differentiation between patients with chronic recurrent multifocal osteomyelitis (CRMO), healthy controls, and alternative diagnoses." (PMID 29250517, 2017). "IL-1 was effective in only 28.6% of patients, while IL-6 was effective in chronic recurrent multifocal osteomyelitis (CRMO) but did not significantly improve skin symptoms." (PMID 41451090, 2025).